ZNF571 (zinc finger protein 571)
Description:
May be involved in transcriptional regulation.
Synonyms: HSPC059
Tractability: Antibody: the Human Protein Atlas places it where antibodies can reach. PROTAC: ubiquitination databases record sites on it.
Gene: Protein-coding gene on chromosome 19 (37,554,782 to 37,595,134, reverse strand). Ensembl gene ENSG00000180479.
Subcellular location: Nucleus
Subcellular location (Human Protein Atlas): Nucleoli; Nucleoplasm; Plasma membrane
Pathways (Reactome):
Gene expression (Transcription): Generic Transcription Pathway
Gene Ontology:
Molecular function: DNA-binding transcription factor activity, RNA polymerase II-specific; RNA polymerase II cis-regulatory region sequence-specific DNA binding
Biological process: regulation of transcription by RNA polymerase II; regulation of DNA-templated transcription
Cellular component: nucleus
Genetic constraint (gnomAD): Loss-of-function variants: 5 observed, 9.08 expected, observed/expected ratio (o/e) 0.55, 90% interval 0.29 to 1.16. That is too few expected variants to judge how well the gene tolerates losing a copy. Missense variants: 702 observed, 762.38 expected, observed/expected ratio (o/e) 0.92, 90% interval 0.87 to 0.98. Synonymous variants: 249 observed, 242.79 expected, observed/expected ratio (o/e) 1.03, 90% interval 0.92 to 1.14.
Homologues: Orthologues: chimpanzee ZNF571 (99% identical), macaque ZNF571 (97% identical). Paralogues in human: ZNF546 (55% identical), ZNF540 (51% identical), ZNF30 (50% identical), ZFP14 (48% identical), ZNF841 (48% identical), ZNF573 (48% identical), ZNF836 (48% identical), ZFP30 (47% identical), ZFP82 (47% identical), ZNF267 (45% identical), ZNF461 (45% identical), ZNF33B (44% identical), and 164 more.